LINC00494 (long independently transcribed non-coding RNA 494)
Gene: Long non-coding RNA gene on chromosome 20 (48,359,884 to 48,370,636, forward strand). Ensembl gene ENSG00000235621.
Diseases named in the same sentence as LINC00494 in open-access papers:
LINC00494 is named in the same sentence as 6 diseases in open-access papers, as found by Europe PMC text mining. Sharing a sentence is not in itself a finding about the gene and the disease. The quoted sentences say what the papers report.
ovarian carcinoma (4 papers, 2020 to 2025). A malignant neoplasm originating from the surface ovarian epithelium. "Linc00494 upregulation accelerated the expression of NF-kappa B1 and caused invasion, migration and tumorigenesis in ovarian cancer cells." (PMID 35928868, 2022). "Therefore, in the current investigation we endeavored to unravel the functional role of LINC00494 in ovarian cancer and to explore the underlying regulatory mechanisms." (PMID 33585183, 2020). "Linc00494 upregulates NF-κB1 expression, thereby promoting the invasion, migration, and tumorigenic potential of ovarian cancer cells." (PMID 40534867, 2025). "Strikingly, linc00494 expression levels were highly upregulated in ovarian cancer tissues, while FBXO32 has a lower expression in ovarian tumor specimens." (PMID 35928868, 2022). "Following the identification of high LINC00494 expression in ovarian cancer, we characterized the functional role of LINC00494 in ovarian cancer." (PMID 33585183, 2020). "In the present study, we showed that LINC00494 expression was significantly upregulated in ovarian cancer, and its knockdown inhibited ovarian cancer cell migration, invasion and tumorigenesis in vivo." (PMID 33585183, 2020). "Ovarian cancer samples in the GSE38666 dataset deposited in the Gene Expression Omnibus (GEO) showed differential expression of LINC00494, which motivated us to characterize further its functional role in the pathogenesis of ovarian cancer." (PMID 33585183, 2020). "In the next experiments, we further investigated the molecular mechanisms behind LINC00494’s involvement in ovarian cancer." (PMID 33585183, 2020). "Moreover, LINC00494 has been found to promote ovarian cancer advancement by regulating FBXO32 via binding and enhancing the activity of the NF-kappaB1 (NF-κB1)." (PMID 40181954, 2025). "However, due to the limited time and funding, we are not allowed to explore the respective roles of FBXO32 and NFκB1 in ovarian cancer, which will be further studied in our future research for better clinical application of LINC00494 knockdown." (PMID 33585183, 2020). "Likewise, LINC00494-specific siRNA was designed and delivered into Caov-3 cells for construction of LINC00494 knockdown ovarian cancer cells." (PMID 33585183, 2020). "Notably, the identification of LINC00494 as a new regulator of ovarian cancer progression offers a fresh molecular insight, with some potential for translational for ovarian cancer." (PMID 33585183, 2020). "Therefore, we performed this study to define better the regulatory role of the LINC00494/NFκB1/FBXO32 axis in the development of ovarian cancer." (PMID 33585183, 2020). "In this study, we found that LINC00494 can bind to the transcription factor NFκB1, and that NFκB1 then binds to the FBXO32 promoter, aggravating ovarian cancer." (PMID 33585183, 2020). "We performed real-time qPCR and immunoblotting analysis to determine the expression levels of LINC00494, NFκB1, and FBXO32 in several ovarian cancer cell lines (Caov-3, A2780, SKOV3, and CoC1) and a normal ovarian epithelial cell line, IOSE80." (PMID 33585183, 2020). "The differentially analysis indicated high expression of LINC00494 and low expression of FBXO32 in ovarian cancer, which was entirely consistent with corresponding findings in clinical cancer tissues and normal tissues." (PMID 33585183, 2020). "Bioinformatics analysis predicted potential interactions among LINC00494, NFκB1, and FBXO32 in ovarian cancer, which were tested by dual-luciferase reporter assay, RNA pull-down, RIP, and ChIP assay." (PMID 33585183, 2020). "In summary, linc00494 modulates the NF-κB1/FBXO32 axis and drives ovarian cancer progression." (PMID 40534867, 2025). "In summary, linc00494 modulated NF-kappa B1 and FBXO32 and enhanced progression of ovarian cancer." (PMID 35928868, 2022).
ovarian carcinoma (continued). "Overexpression of LINC00494 elevated NFκB1 expression and enhanced cell migration, invasion and tumorigenesis, but additional overexpression of FBXO32 interfered with the tumorgenicity of ovarian cancer cells in vitro and in vivo." (PMID 33585183, 2020).
Cirrhosis (1 paper, 2020). A chronic disorder of the liver in which liver tissue becomes scarred and is partially replaced by regenerative nodules and fibrotic tissue resulting in loss of liver function. "Univariate analysis identified the following 11 lncRNAs as significantly correlated with RFS of patients with cirrhosis: SH3RF3-AS1, AC104117.3, AC136475.3, LINC00239, MRPL23-AS1, LINC00494, LINC01970, MEG3, Z93930.3, MIR9-3HG and TRBV11-2." (PMID 32592379, 2020).
Obesity (1 paper, 2022). Accumulation of substantial excess body fat. "For those 12 genes, six of them (DDO, SEPT9, TMEM45B, RXRα, ZNF395 and AHRR) were previously reported to be implicated in the obesity or related diseases and the rest six were novel (PACRG, LINC00494, KLHL4, DTX1, VCX3A and VSTM1)." (PMID 35568907, 2022).
cancer (2 papers, 2020 to 2024). A tumor composed of atypical neoplastic, often pleomorphic cells that invade other tissues. "Several genes, including ARRDC5, ELF5, FIBCD1, LINC00494, NLRP7, and L1CAM, have been implicated in various aspects of cancer progression and metastasis." (PMID 39697539, 2024). "Relative to IOSE80, all cancer cell lines exhibited upregulated expression levels of LINC00494 and NFκB1 as well as downregulated expression level of FBXO32." (PMID 33585183, 2020). "Through comprehensive genomic, epigenomic, and transcriptomic dissections, we pinpointed ARRDC5, ELF5, FIBCD1, LINC00494, NLRP7, and L1CAM as possible prognostic indicators across multiple cancer types." (PMID 39697539, 2024). "In this study, we examined the expression patterns of seven core genes (ARRDC5, ELF5, FIBCD1, LINC00494, NLRP7, L1CAM) across multiple cancer types using a combination of unpaired and paired samples, along with data from the TCGA-GTEx datasets." (PMID 39697539, 2024).
tumor (1 paper, 2020). "Analysis at six weeks after implantation showed that overexpression of LINC00494 increased tumor weight and volume while silencing of LINC00494 had opposite effects." (PMID 33585183, 2020). "Taken together, overexpression of LINC00494 promoted the xenograft tumor growth and silencing of LINC00494 exerted an opposite effect." (PMID 33585183, 2020).
LINC00494 also shares sentences with these, for which no sentence is quoted: asthma (1 paper).